PPARA (peroxisome proliferator activated receptor alpha)
Diseases named in the same sentence as PPARA in open-access papers (continued):
Sharing a sentence is not in itself a finding about the gene and the disease.
infection (continued). "We previously demonstrated that fenofibrate, PPARα agonist, controls inflammation, prevents fibrosis and improves cardiac function in a murine infection model." (PMID 35360222, 2021). "To better understand the biological relevance of nhr-49/PPARA to the infection-specific host response, we compared the transcriptomes of starved and infected nhr-49/PPARA mutants." (PMID 33978570, 2021). "Infection with Francisella tularensis heavily upregulates fatty acid metabolism, which we already know is regulated by the PPARα pathway." (PMID 35003101, 2021). "Consistently, expression in each of these tissues also rescued the infection survival defect of nhr-49/PPARA mutants." (PMID 33978570, 2021). "In contrast, in infected hlh-30/TFEB mutants compared with wild type, nhr-49/PPARA expression was lower, indicating that HLH-30/TFEB contributes to nhr-49/PPARA expression during infection." (PMID 33978570, 2021). "Because hlh-30/TFEB and nhr-49/PPARA contributed to both infection-specific fmo-2/FMO5 induction and each other’s expression, we examined their genetic interactions." (PMID 33978570, 2021). "Further, infection with PPARα-expressing adenovirus restored cell viability in HNE-stressed cells (p ≤ 0.05)." (PMID 30716067, 2019). "Further, we found that infection with PPARα-expressing adenovirus decreased ROS production in 4-HNE-stressed cells (p ≤ 0.05)." (PMID 30716067, 2019). "CCR5-/- mice were extremely susceptible to infection, presenting higher parasite load and lower tissue expression of IL-12p40, IFN-γ, TNF, IL-6, iNOS, Foxp3, T-bet, GATA-3 and PPARα." (PMID 25119429, 2014). "Our gene expression data pointed to decreased expression of PPARα in the liver of CCR5-/- infected mice at the 8th day after infection." (PMID 25119429, 2014). "One of the non-coding variants is located at chr2∶49,202,765 in a putative binding site for peroxisome proliferator-activated receptor alpha (PPARA), which has been implicated with preterm birth complicated with infection." (PMID 24205076, 2013). "In our experiments PPARα was increased following infection in both AFL and ASL, indicating increased lipid metabolism within the peroxisome." (PMID 20602791, 2010). "In this study, fenofibrate, a peroxisome proliferator-activated receptor alpha (PPARα) agonist, effectively suppressed M. bovis replication and infection (both in vitro and in vivo) by restoring autophagic flux and reprogramming intracellular cholesterol homeostasis." (PMID 41602117, 2026). "After infection with the intestinal parasite Giardia muris, rapid PPARα induction did not affect the protective or pathological immune responses; PPARα-deficient mice cleared the parasite as did wild-type controls." (PMID 36831317, 2023). "This diaphonic relationship between the reprogramming of the cellular metabolism and infection could therefore be disrupted by agonists of the AdipoR1/AMPK/PPARα axis." (PMID 38257725, 2023). "We wondered if PPARα agonist effects could promote virus replication even if cells were treated with agonist after infection, or if the effects of agonist required pretreatment." (PMID 36715509, 2023). "It is important to clarify whether PPARα modulates lipid body formation during infections with Mabc and other NTMs." (PMID 36831317, 2023). "Fat ablation further increased lipid oxidation as evidenced by increased PPARα and SOD during infection which could have caused a further increase in cardiac ER stress." (PMID 33826636, 2021). "Such a metabolic signature suggests that infection impairs PPARα signaling." (PMID 34638886, 2021). "Moreover, relative to wild type, two distinct nhr-49/PPARA gain-of-function mutants showed enhanced infection survival." (PMID 33978570, 2021). "Therefore, hlh-30/TFEB deletion completely suppressed the enhanced survival phenotypes of nhr-49/PPARA gain-of-function alleles, which is consistent with hlh-30/TFEB functioning downstream of nhr-49/PPARA for host infection survival." (PMID 33978570, 2021).
infection (continued). "Transgenic rescue of nhr-49/PPARA driven by its endogenous promoter completely rescued the infection survival defect but only partially restored the total lifespan on E. coli, suggesting that distinct thresholds of NHR-49/PPAR-α function exist in infection and aging." (PMID 33978570, 2021). "Comparable to fenofibrate, pemafibrate reduced bacterial loads in circulation and target organs, indicating that through modulation of PPARα expression and metabolic pathways, pemafibrate may assist in the control of tissue infection and damage." (PMID 31916705, 2020). "Peroxisome proliferator receptor-α (Pparα) was unaffected by infection." (PMID 31299982, 2019). "Infection and inflammation induced fatty acids oxidation decreasing and lipid synthesis enhancing are regulated by several transcriptional factors and enzymes, like PPARα and SREBP-1c." (PMID 30398974, 2018). "Taken together, all these considerations suggestthat PPARα/γ may represent new potential therapeutic targets inHCV infection." (PMID 19343188, 2009). "This may be indirect evidence that infection with F. tularensis leads to PPARα activation." (PMID 35003101, 2021). "The effects of PPAR activation on MHV68 replication were examined by treating BMDMs with agonists for PPARα (fenofibrate or WY14643), PPARβ/δ (GW501516), or PPARγ (rosiglitazone) prior to infection." (PMID 36715509, 2023). "The levels of PPARα significantly increased in both RD-fed infected and MFD-fed infected mice during acute infection and only in MFD-fed infected mice during chronic infection compared to uninfected RD-fed mice." (PMID 36676177, 2023). "Conversely, in nhr-49/PPARA null mutants hlh-30/TFEB baseline expression was higher than in wild type, yet its induction by infection was abrogated." (PMID 33978570, 2021). "Simultaneous deletion of nhr-49/PPARA and fmo-2/FMO5 resulted in similarly impaired infection survival as the single mutants, suggesting that nhr-49/PPARA and fmo-2/FMO5 function in the same pathway." (PMID 33978570, 2021). "(A–F) Epifluorescence micrographs of animals carrying Pfmo-2::nls::gfp in wild type (A, B), hlh-30/TFEB (C, D), and nhr-49/PPARA mutant backgrounds (E, F) after feeding on E. coli OP50 or infection with S. aureus SH1000 (4 hr)." (PMID 33978570, 2021). "This indicates that PPARα regulates the ILC3 effector functions, which are important for both fighting infections and sustaining tolerance to commensal microbiota." (PMID 34638886, 2021). "In this context, an impaired expression of PPARα, most likely influenced by HCV core protein, has been reported during the infection in patient-derived liver cells." (PMID 33134318, 2020). "Infection significantly increased hepatic PPARα levels compared to uninfected RD mice, and infected HFD mice showed significantly greater levels of PPARα compared to infected RD mice." (PMID 31949545, 2019). "PPARα or PPARγ agonists reverted the infection-induced JNK and ERK phosphorylation while PPARα and PPARγ antagonist enhanced these phosphorylations." (PMID 29875768, 2018). "Previous studies reported that infection and inflammation increased the expression of SREBP-1c and its target genes, like FAS and ACC, while inhibited the expression of PPARα in vivo and in vitro." (PMID 30398974, 2018). "Moreover, 92 (68%) of the 135 infection-upregulated genes in wild type were also upregulated in nhr-49/PPARA mutants, and we categorized them as NHR-49/PPAR-α-independent." (PMID 33978570, 2021). "Only 43 genes were induced by infection in wild type but not in nhr-49/PPARA mutants, and thus we categorized them as NHR-49-dependent." (PMID 33978570, 2021). "During infection, nhr-49/PPARA expression did not change in wild-type animals compared to uninfected controls." (PMID 33978570, 2021).
infection (continued). "In the present study, 109 CFUs/mL E. coli could up-regulate the expression of hepatic SREBP-1c, ACC1 (one subset of ACC) and FAS, and down-regulate the expression of PPARα and CPT-1α, which was accordance with LPS-induced infection in CD-1 mice." (PMID 30398974, 2018). "After infection, nhr-49/PPARA mutants completely failed to induce fmo-2/FMO5." (PMID 33978570, 2021). "However, our data suggest that the antiviral activity of fenofibrate measured in the infection assays presented here is not mediated by the transcription factor PPARα." (PMID 34421587, 2021). "We then demonstrated that AMPK phosphorylation levels decrease significantly upon infection (p < 0.05), which is accompanied by decreased phosphorylation of ACC, the transcription factor sterol regulatory element binding protein-1c (SREBP-1c), and PPARα (p < 0.001)." (PMID 31604978, 2019). "We cannot rule out either the modulation of infection by PPARα functions in inflammatory processes." (PMID 25242866, 2014). "Importantly, the effects of fibrates on the preservation of neutrophil functionality and improved infection control were independent of PPARα expression, as confirmed by experiments using Pparα−/− mice." (PMID 24755316, 2014). "Subsequent work showed that nhr-49/PPARA silencing impaired infection survival of E. faecalis, but the connection between nhr-49/PPARA and fmo-2/FMO5 during infection was not established until our present work and that of others." (PMID 33978570, 2021). "PPARα/RXRα activation, Wnt/β-catenin signaling, GNRH signaling cAMP-mediated signaling, and ERK/MAPK signaling are the most prominent among the signaling pathways significantly affected by PR8 infection but were not impacted by the infection in CLIC1 KD cells." (PMID 38257829, 2024).
cardiovascular disease (92 papers, 2005 to 2026). "The loss of PPARα in the liver caused hepatic lipid accumulation in chow-fed mice, which was worsened with high-fat feeding, and the hepatic loss of PPARα leads to cardiovascular disease." (PMID 40985048, 2025). "Radiation-induced cardiovascular disease is associated with metabolic remodeling in the heart, mainly due to the inactivation of the transcription factor peroxisome proliferator-activated receptor alpha (PPARα), thereby inhibiting lipid metabolic enzymes." (PMID 34944662, 2021). "There is only one report on the association between the PPARα G/C polymorphism and cardiovascular disease events." (PMID 22347658, 2011). "A growing body of evidence describes associations between the PPARα gene and cardiovascular disease, risk or outcomes in subjects with type 2 DM." (PMID 20838448, 2010). "In terms of thrombosis, PPARα may affect platelet function and expression of clotting factors, and inhibit thrombosis, which is an important risk factor for cardiovascular diseases." (PMID 40650120, 2025). "LPL, apoE, and PPARα are known as important components of lipid metabolism with roles in the homeostasis of different lipoprotein fractions and their transport, and the polymorphisms of these genes have been associated with cardiovascular diseases." (PMID 25242866, 2014). "This strong PPARα agonist is also widely used in academic research to study various metabolic and cardiovascular disorders." (PMID 41882825, 2026). "PPARα is well known for its role in vascular function, and PPARα agonists such as clofibrate, fenofibrate, and gemfibrozil are used in the clinic as antilipemic agents to manage cardiovascular disease." (PMID 40362325, 2025). "Numerous reports have indicated that the PPARA gene regulatory pathway influences cardiovascular diseases through its role in metabolic regulation." (PMID 41008965, 2025). "In fact, PPARα agonists such as fenofibrate, gemfibrozil, and bezafibrate are used in the clinic to manage cardiovascular disease by dampening inflammation, reducing triglyceride levels, and increasing beneficial HDL cholesterol." (PMID 40362325, 2025). "Ginsenoside Rg1 and ginsenoside Rg3 demonstrate potential for treating cardiovascular diseases, with ginsenoside Rg1 activating PPARα promoter, and the PI3K/Akt pathway." (PMID 40002867, 2025). "Activation of peroxisome proliferator–activated receptors (PPARs), including PPARα, PPARβ/δ, and PPARγ, has been shown to exert beneficial effects in cardiovascular diseases such as atherosclerosis and MI." (PMID 37018396, 2023). "For example, PPARα agonists, PPARγ agonists, and MR antagonists are all clinically approved and commonly used to treat patients with metabolic and/or cardiovascular diseases." (PMID 37018396, 2023). "For instance, PPARα-agonists, fibrates, have shown vital benefit in treating cardiovascular disease in clinical and NAFLD in rodents." (PMID 35528835, 2022). "PPARα agonists have a favorable effect on the reduction of cardiovascular disease by preventing the progression of arterial lumen occlusion and PPARα activation results in direct antiatherogenic effect in the artery walls." (PMID 28656106, 2017). "The effects we observed in Pparα−/− mice have potentially significant consequences for cardiovascular disease." (PMID 26649033, 2015). "The role of PPARα in cardiovascular disease is an interesting area for research because of its association with fatty acid oxidation, lipid metabolism, and inflammation." (PMID 22347658, 2011). "Until now, only PPARα agonists (e.g., fibrates) have been in clinical use for lipid lowering, the prevention of atherosclerosis, and cardiovascular disease, while PPARγ agonists (e.g., thiazolidinediones) lower glucose by increasing insulin sensitivity, mainly in skeletal muscle and adipose tissue." (PMID 35954274, 2022). "The previous report showed inconsistent expression of PPARα in cardiovascular diseases." (PMID 32922293, 2020).
cardiovascular disease (continued). "Both PPARα and PPARβ/δ have overlapping functions in cardiovascular diseases." (PMID 30287730, 2018). "All these evidences support a linkage between PPARα and cardiovascular diseases." (PMID 27000070, 2016). "Our findings highlight the significant role PPARα may play in cardiovascular disease via suppression of ROS and maintenance of endothelial function." (PMID 26649033, 2015). "Importantly, PPARα agonists are effective in raising HDL-cholesterol and lowering triglycerides, properties that reduce the risk for cardiovascular diseases." (PMID 23967086, 2013). "Some of the master regulators identified in WAT in the present study (Jun, Fos, Rarα, Pparα, Stat1, Stat5, Sp1) were also reported to control liver lipid metabolism and/or the inflammatory responses of the liver in experimental diet-induced cardiovascular disease." (PMID 24086498, 2013). "Taken together, fenofibrate might be a special fibrate drug that not only lowers plasma triglyceride and reduces inflammation by activating PPARα to improve cardiovascular diseases, but also regulates Th17, Th1 and Treg differentiation independent PPARα." (PMID 22792085, 2012). "In recent clinical trials, PPARα agonists have been shown to be effective in the primary prevention of cardiovascular events, while their cardiovascular benefit in patients with established cardiovascular disease remains equivocal." (PMID 18288280, 2008). "PPARα agonists, such as the fibrate class of drugs, are effective in the treatment of dyslipidemia, where they raise HDL and reduce serum triglycerides, properties that decrease incidence of atherosclerosis and reduce risk for the development of cardiovascular disorders." (PMID 23967086, 2013). "A down-regulation of mitochondrial biogenesis markers, including Nrf2, PPARα, and PGC-1α expression, has been reported in the animal models of doxorubicin-induced cardiotoxicity and some other cardiovascular disorders." (PMID 39469220, 2024). "PPARα transcriptionally activates the cell-cycle regulator p16Ink4a via a PPAR-response element and an SP1-binding site, and inhibits smooth-muscle cell proliferation, which is relevant to the prevention of intimal hyperplasia in cardiovascular disease." (PMID 35954274, 2022). "Later trials with Aleglitazar, also a dual PPARα and γ agonist, had to be stopped due to excess adverse events, making this class of therapeutics unlikely to be successful in the treatment of cardiovascular disease in diabetic patients." (PMID 33322384, 2020). "Protection against cardiovascular disease by PPARα agonists may therefore result from long-term genomic, nonspecific acute effects in the cardiovascular system." (PMID 23008696, 2012). "In larger clinical studies, the dual PPARα/γ agonist aleglitazar (AleCardio and ALEPREVENT randomized clinical trials) showed no significant improvement of cardiovascular disease, but multiple significant side effects." (PMID 32785018, 2020).
kidney disease (37 papers, 2009 to 2026). "Accumulating evidence established that all PPAR members (PPARα, PPARβ/δ, and PPARγ) are implicated in the pathogenesis of kidney diseases." (PMID 40432888, 2025). "Therefore, pemafibrate is potentially more effective in decreasing the triglyceride levels and inflammation than other existing PPARα agonists, thereby inhibiting dyslipidemia‐associated diseases, including cardiovascular and renal disorders." (PMID 39887648, 2025). "Furthermore, it has been shown that renal disease, including albuminuria, is more severe in diabetic mice that are genetically deficient for PPARα than in wild-type mice." (PMID 21311715, 2011). "PPARα is one of the key regulators for ketone body synthesis, and ketone bodies exert beneficial effects on kidney disease." (PMID 39887648, 2025). "Among the PPAR isoforms, PPARα plays a particularly prominent role in renal disease, exerting complex and multifaceted regulatory effects." (PMID 41345744, 2025). "Top healthy-promoting TFs included canonical PT TFs, HNF4A and PPARA, as well as other factors that have been demonstrated to be protective against kidney disease: ESRRG and RREB149,56–58." (PMID 38347009, 2024). "PPARα and FAO-associated gene expression was decreased with age, which is directly related to the lipid metabolic disturbances in renal diseases in aged." (PMID 35308207, 2022). "Some studies have shown that restoration of PPARα activity and/or expression is a potential treatment strategy for preventing the progression of kidney diseases." (PMID 35517820, 2022). "PPARα is highly expressed in the proximal tubules and participates in the occurrence and development of kidney diseases." (PMID 34541006, 2021). "With the current results, we speculate that PPARα in PT has a renoprotective role, and have planned further experiments using kidney disease models on Ppara∆KPT to clarify this issue." (PMID 41460648, 2026). "Further assessment of the association between PPARα and GNG could help develop novel treatment strategies for kidney diseases." (PMID 41460648, 2026). "Collectively, our findings suggest PPARα as a potential therapeutic target for kidney diseases." (PMID 39887648, 2025). "Taken together, these findings suggest that PPARα may be a novel therapeutic target for the treatment of kidney disease." (PMID 35308207, 2022). "Pemafibrate (PEM), a novel selective PPARα modulator, is mainly excreted in bile, and, thus, may be safe and effective in kidney disease patients." (PMID 34207854, 2021). "It has been demonstrated that PPARα and γ agonists have renoprotective effects in proteinuric kidney diseases; however, the role of PPARδ agonists in kidney diseases remains unclear." (PMID 21966476, 2011). "Regulation of PPARα activity factors, including PPARα gene expression and protein translation, ligand specificity and availability, cofactor recruitment, corepressors or coactivators, and posttranslational modification, is an effective strategy to prevent and treat lipid disorders in kidney disease." (PMID 35526054, 2022). "PPARα, AMPK, sirtuins, HIF-1, and TGF-β/SMAD3 activation have all been shown to play key roles in the regulation of fatty acid β-oxidation in kidney diseases, and restoration of fatty acid β-oxidation by modulation of these molecules can ameliorate the development of such diseases." (PMID 35517820, 2022).